NCOA2 (nuclear receptor coactivator 2)
Description:
Transcriptional coactivator for steroid receptors and nuclear receptors. Coactivator of the steroid binding domain (AF-2) but not of the modulating N-terminal domain (AF-1). Required with NCOA1 to control energy balance between white and brown adipose tissues. Critical regulator of glucose metabolism regulation, acts as a RORA coactivator to specifically modulate G6PC1 expression. Involved in the positive regulation of the transcriptional activity of the glucocorticoid receptor NR3C1 by sumoylation enhancer RWDD3. Positively regulates the circadian clock by acting as a transcriptional coactivator for the CLOCK-BMAL1 heterodimer (By similarity).
Synonyms: NCoA-2; bHLHe75; SRC2; TIF2; SRC-2; GRIP1; KAT13C
Tractability: Small molecule: a structure with a bound ligand is known. PROTAC: UniProt records ubiquitination sites on it; ubiquitination databases record sites on it; its protein half-life has been measured; a small molecule that binds it is known.
Gene: Protein-coding gene on chromosome 8 (70,109,772 to 70,404,191, reverse strand). Ensembl gene ENSG00000140396.
Subcellular location: Nucleus
Subcellular location (Human Protein Atlas): Nuclear bodies; Nucleoplasm
Pathways (Reactome):
Metabolism: Activation of gene expression by SREBF (SREBP); Endogenous sterols; PPARA activates gene expression; Recycling of bile acids and salts; Regulation of lipid metabolism by PPARalpha; Synthesis of bile acids and bile salts; Synthesis of bile acids and bile salts via 27-hydroxycholesterol; Synthesis of bile acids and bile salts via 7alpha-hydroxycholesterol
Circadian clock: BMAL1:CLOCK,NPAS2 activates circadian expression; Expression of BMAL (ARNTL), CLOCK, and NPAS2; RORA,B,C and NR1D1 (REV-ERBA) regulate gene expression
Cellular responses to stimuli: Cytoprotection by HMOX1; Heme signaling
Signal Transduction: Activated PKN1 stimulates transcription of AR (androgen receptor) regulated genes KLK2 and KLK3; Estrogen-dependent gene expression
Chromatin organization: HATs acetylate histones
Developmental Biology: Transcriptional regulation of white adipocyte differentiation
Gene expression (Transcription): MLL4 and MLL3 complexes regulate expression of PPARG target genes in adipogenesis and hepatic steatosis
Metabolism of proteins: SUMOylation of transcription cofactors
Organelle biogenesis and maintenance: Transcriptional activation of mitochondrial biogenesis
Gene Ontology:
Molecular function: aryl hydrocarbon receptor binding; nuclear receptor binding; protein binding; protein domain specific binding; transcription coactivator activity; transcription regulator inhibitor activity; transcription coregulator activity; chromatin binding; protein dimerization activity; RNA polymerase II cis-regulatory region sequence-specific DNA binding; RNA polymerase II intronic transcription regulatory region sequence-specific DNA binding; RNA polymerase II-specific DNA-binding transcription factor binding; signaling receptor binding
Biological process: negative regulation of smoothened signaling pathway; positive regulation of transcription by RNA polymerase II; bile acid and bile salt transport; cellular response to hormone stimulus; circadian regulation of gene expression; mRNA transcription by RNA polymerase II; peroxisome proliferator activated receptor signaling pathway; positive regulation of adipose tissue development; regulation of cellular response to insulin stimulus; regulation of DNA-templated transcription; regulation of lipid metabolic process; circadian rhythm; locomotor rhythm; regulation of glucose metabolic process
Cellular component: nuclear body; nucleoplasm; nucleus; protein-containing complex; RNA polymerase II transcription regulator complex; transcription regulator complex; chromatin; cytoplasm
Genetic constraint (gnomAD): Loss-of-function variants: 21 observed, 143.08 expected, observed/expected ratio (o/e) 0.15, 90% interval 0.1 to 0.21. The upper end of that interval is the gene's LOEUF score, 0.21, which puts it in group 1 of 6, group 1 being the genes least tolerant of losing a copy. Missense variants: 1,471 observed, 1,911.3 expected, observed/expected ratio (o/e) 0.77, 90% interval 0.74 to 0.8. Synonymous variants: 619 observed, 669.43 expected, observed/expected ratio (o/e) 0.92, 90% interval 0.87 to 0.99.
Cancer hallmarks: proliferative signalling (promotes); angiogenesis (promotes); tumour promoting inflammation (suppresses); invasion and metastasis (suppresses); change of cellular energetics (promotes); escaping programmed cell death (promotes); suppression of growth (promotes); escaping programmed cell death (suppresses); invasion and metastasis (promotes)
Homologues: Orthologues: chimpanzee NCOA2 (100% identical), macaque NCOA2 (99% identical), dog NCOA2 (97% identical), guinea pig NCOA2 (97% identical), rabbit NCOA2 (96% identical), mouse Ncoa2 (94% identical), rat Ncoa2 (93% identical), pig NCOA2 (91% identical), tropical clawed frog ncoa2 (74% identical), zebrafish ncoa2 (60% identical), Drosophila melanogaster tai (25% identical). Paralogues in human: NCOA3 (41% identical), NCOA1 (35% identical).
Diseases named in the same sentence as NCOA2 in open-access papers:
NCOA2 is named in the same sentence as 105 diseases in open-access papers, as found by Europe PMC text mining. Sharing a sentence is not in itself a finding about the gene and the disease. The quoted sentences say what the papers report.
prostate carcinoma (24 papers, 2007 to 2025). A carcinoma that arises from epithelial cells of the prostate gland. "NCOA2 is implicated in the processes of metastasis and castration resistance observed in prostate cancer." (PMID 40575382, 2025). "The upregulated gene set included oncogenes such as PIK3CB, FGFRL1, and NCOA2; prostate cancer-related genes such as SPON2, PCAT4, and SCHLAP1; and cell cycle genes such as MKI67, MCM4, KIF4A, CENPF, and FLNB." (PMID 38067373, 2023). "For example, evidence for cooperation between AR and NCOA2 amplifications on 8q13.3 in early prostate cancer was reported." (PMID 23561577, 2013). "Although it was suggested that HSP90AA1 could be a potential target for NSCLC treatment, another protein-coding gene, NCOA2, might be relevant for gastric cancer, liver cancer, or prostate cancer." (PMID 35256890, 2022). "Therefore we included NCOA2 both as a positive control in our studies and to confirm that this regulation is conserved in prostate cancer." (PMID 26461474, 2015). "One of the findings we were able to retrieve using the integrative approach is the nuclear receptor coactivator NCOA2 that was previously shown to alter AR pathway in primary prostate tumors providing mechanism for its potential role as a prostate cancer oncogene." (PMID 22811706, 2012). "NCOA2 is another coregulator that may be involved in prostate cancer." (PMID 40023399, 2025). "The nuclear receptor coactivator NCOA2 may also be altered in some prostate cancers." (PMID 22901743, 2012). "Inferring that PPARD also represses NCOA2's activity, provides another clue for PPARD's inactivation in prostate cancer progression." (PMID 19640296, 2009). "Knockdown of NCOA2 in a prostate cancer cell line cultured with DHT and the antiandrogen bicalutamide increased proliferation, suggesting that NCOA2 may inhibit prostate cancer growth." (PMID 40023399, 2025). "Such as ADT treatment induces the up-regulated expression of Nuclear receptor coactivator 2(NCoA2), which could activate the PI3K signaling pathway to promote prostate cancer metastasis and CRPC." (PMID 36506053, 2022).
leukemia (16 papers, 2008 to 2025). A malignant (clonal) hematologic disorder, involving hematopoietic stem cells and characterized by the presence of primitive or atypical myeloid or lymphoid cells in the bone marrow and the blood. "Moreover, NCOA2 gene fusions have been identified in multiple cancer types, including spindle cell sarcomas, leukemia, rhabdomyosarcoma, and uterine sarcoma." (PMID 40575382, 2025). "Several genes that we identified included IDH2, NCOA2, IKZF1 and BLM described as being involved in leukemia." (PMID 37174060, 2023). "Amongst pluripotency genes, we have identified cancer genes (IDH2, NCOA2, IKZF1, BLM) which are already described as being involved in leukemia." (PMID 37174060, 2023). "Furthermore, since NCOA2 gene fusion can also occur in other malignancies, such as leukemia and sarcomas, NCOA2 is not a specific genetic marker for AFST." (PMID 39432588, 2024).
rhabdomyosarcoma (15 papers, 2014 to 2025). A rare aggressive malignant mesenchymal neoplasm arising from skeletal muscle. "This supports the rationale to further explore ARF6 as a therapeutic target for VGLL2::NCOA2-driven rhabdomyosarcoma and highlights the zebrafish system as a model to understand new biology." (PMID 40599857, 2025). "PAX3::NCOA1 and PAX3::NCOA2 fusions are found in rhabdomyosarcoma." (PMID 40599857, 2025). "Moreover, SRF::NCOA2 fusion-positive pediatric RMS (rhabdomyosarcoma) showing diffuse staining for desmin and multifocal nuclear positivity for myogenin are reported." (PMID 36421692, 2022). "In pediatrics, NCOA2 rearrangements have been identified in acute leukemia and rhabdomyosarcoma." (PMID 26146478, 2015). "Spindle cell/sclerosing rhabdomyosarcomas typically harbor certain genomic alterations, including rearrangements involving TFCP2, VGLL2, NCOA2, CITED2, TEAD1, and SRF, as well as the MYOD1 p.L122R mutation." (PMID 40361368, 2025). "Notably, NCOA2 has been detected as a fusion partner in numerous other malignancies, including acute myeloid leukaemia (MYST3-NCOA2), other types of acute leukaemia (ETV6-NCOA2), subtypes of alveolar rhabdomyosarcoma (PAX3-NCOA2) and, recently, benign soft tissue angiofibromas (AHHR-NCOA2)." (PMID 25202377, 2014).
mesenchymal chondrosarcoma (13 papers, 2014 to 2026). A morphologic variant of chondrosarcoma arising from bone and soft tissue. "According to the primary diagnosis in this cohort, we also detected H3F3A in giant cell tumor of bone and malignant giant cell tumor of bone, IDH1/IDH2 mutations in chondrosarcoma, and NCOA2 fusion in mesenchymal chondrosarcoma." (PMID 35756627, 2022). "Newer findings also question well-accustomed “golden rules” including the detection of HEY1::NCOA2 fusions in tumors other than mesenchymal chondrosarcoma and reports on rare USP6-rearranged cases of malignant nodular fasciitis." (PMID 38231260, 2024). "Most cases of mesenchymal chondrosarcoma are associated with a recurrent fusion between HEY1 and NCOA2 resulting from intrachromosomal deletion of 8q." (PMID 37212282, 2023). "In support of this idea, Sox9 expression was maintained upon HEY1::NCOA2 introduction throughout the carcinogenic process of mesenchymal chondrosarcoma, as Sox9 is expressed at high level in eSZ cells." (PMID 37212282, 2023). "Our findings show 2 variants of the HEY1-NCOA2 gene fusion: HEY1 (exon 4)-NCOA2 (exon 13) and HEY1 (exon 4)-NCOA2 (exon 14), in both mesenchymal chondrosarcoma patients." (PMID 30819134, 2019). "The pathogenetic mechanisms behind this nonrandom involvement are unknown, but the presence on 8q of two genes, HEY1 and NCOA2, now known to be involved in mesenchymal chondrosarcoma tumorigenesis is, of course, suggestive." (PMID 24839999, 2014). "Mesenchymal chondrosarcoma affects adolescents and young adults, and most cases usually have the HEY1::NCOA2 fusion gene." (PMID 37212282, 2023). "More recently, recurrent hairy/enhancer-of-split related with YRPW motif 1—nuclear receptor coactivator 2 (HEY1-NCOA2) and interferon regulatory factor 2 binding protein 2 gene—caudal type homeobox 1 (IRF2BP2-CDX1) fusions have been identified in mesenchymal chondrosarcomas." (PMID 36674874, 2023).
chondrosarcoma (12 papers, 2012 to 2025). A malignant cartilaginous matrix-producing mesenchymal neoplasm arising from the bone and soft tissue. "This study demonstrated that human HEY1::NCOA2 expression in embryonic chondrogenic progenitors successfully developed mesenchymal chondrosarcoma." (PMID 37212282, 2023). "HEY1-NCOA2 expression was predominantly detected in the immature component of human mesenchymal chondrosarcoma using the antibody recognizing the NCOA2 C-terminal region." (PMID 37212282, 2023). "Finally, shRNA-mediated gene silencing of HEY1::NCOA2 abrogated growth of mesenchymal chondrosarcoma cells in vitro, indicating that the survival and proliferation of mesenchymal chondrosarcoma are dependent on HEY1::NCOA2 expression." (PMID 37212282, 2023). "Runx2, which is important for differentiation and proliferation of the chondrocytic lineage, is invariably expressed in mouse mesenchymal chondrosarcoma, and interaction between HEY1-NCOA2 and Runx2 is observed using NCOA2 C-terminal domains." (PMID 37212282, 2023).
breast carcinoma (11 papers, 2009 to 2025). "Furthermore, NCOA2 is associated with fibrosis and is essential for the epithelial-mesenchymal transformation in breast cancer cells." (PMID 36059967, 2022). "Interestingly, NCOA2 is widely known for its oncogenic role, and NCOA2 gene fusion, mutations, deletions, insertions and overexpression have been observed in multiple cancers, including endometrial cancer, pleural cancer and breast cancer." (PMID 31751430, 2019). "In summary, our findings show that NCOA2 is frequently amplified in breast cancer and loss of NCOA2 remarkably attenuates cell growth in breast cancer cell lines with different NR status, strongly indicating that NCOA2 might be a potential target for breast cancer treatment." (PMID 30941313, 2019). "The results indicated that high expression levels of OPN4, NOS2, GPR157, NCOA2, CLOCK, and TH were associated with shorter OS in breast cancer patients, while high expression of EGR3, NR1H3, RELB, SIAH2, and ADRB1 was linked to improved survival rates." (PMID 41031266, 2025). "The reduction of NCOA2 expression can induce breast cancer cell apoptosis by regulating the MAPK-ERK signaling pathway." (PMID 33536908, 2020). "To evaluate the biological role of NCOA2 in human breast cancer, we applied lentivirus-mediated RNA interference toward NCOA2 in three breast cancer cell lines (MDA-MB-231, ERα-, PR–, and HER2–; T47D, ERα+, PR+, and HER2–; MCF7, ERα+, PR+, and HER2+/–)." (PMID 30941313, 2019). "In conclusion, our results suggest NCOA2 as a potential target of therapeutics against breast cancer." (PMID 30941313, 2019). "Next, we confirmed that NCOA2 silencing significantly suppressed cell proliferation in different breast cancer cell lines, by inducing cell cycle arrest and apoptosis." (PMID 30941313, 2019). "Both colony formation and MTS cell proliferation assays indicated that NCOA2 knockdown significantly suppressed cell proliferation in different breast cancer cell lines." (PMID 30941313, 2019). "We found that the copy number of the NCOA2 gene was frequently amplified in four breast cancers datasets, varying from 6 to 10%, and the mRNA levels of NCOA2 were also upregulated in 11% of the sequenced cases/patients (TCGA provisional dataset)." (PMID 30941313, 2019). "In this study, we investigated the role of NCOA2 in regulating cell growth of breast cancer cells with different hormone receptor status." (PMID 30941313, 2019). "Here, we showed that NCOA2 is amplified and overexpressed in around 10% breast cancer samples in the TCGA data set, and higher NCOA2 expression correlated with a poor overall survival status." (PMID 30941313, 2019). "While the functions of NCOA1 and NCOA3 have been widely explored in breast cancer, little is known about the biological roles of NCOA2 in regulating genes involved in breast cancer progression." (PMID 30941313, 2019). "However, the biological roles of NCOA2 in breast cancer, especially in triple negative breast cancers (TNBC) remain elusive." (PMID 30941313, 2019). "Further, to determine whether RASEF downregulation accounted for the anti-proliferative effect of NCOA2 depletion, we assessed breast cancer cell growth after RASEF knockdown in MTS cell proliferation and colony formation assays." (PMID 30941313, 2019). "Furthermore, WB analysis confirmed that when NCOA2 was depleted in breast cancer cells, the activity of the MAPK/ERK signaling was strongly inhibited, as represented by the decreased protein levels of p-MEK and p-ERK." (PMID 30941313, 2019). "However, the biological function of NCOA2 in breast cancer is not fully understood." (PMID 30941313, 2019). "Although NCOA2 depletion in MCF-7 cells has been shown to suppress estrogen-dependent ERα transactivation function, it does not seem to affect the estrogen-dependent proliferation of these cells, suggesting an ERα-independent role for NCOA2 may exist in breast cancer." (PMID 30941313, 2019).
breast carcinoma (continued). "Further, analysis of breast cancer tissue data from the TCGA database showed that RASEF and NCOA2 levels were strongly and positively correlated (R = 0.51, P < 0.0001)." (PMID 30941313, 2019). "Gene amplification and overexpression of NCOA1, NCOA2 and NCOA3 in breast cancer has been described previously by several groups thus contributing to the development of cancer." (PMID 24304549, 2013). "Applying quantitative real-time RT-PCR (qRT-PCR), Western Blot analysis and chromatin immunoprecipitation, we analyzed the involvement of NCOA1, NCOA2, NCOA3 in the ERα-mediated transactivation of PLAC1 in the breast cancer cell lines MCF-7 and SK-BR-3." (PMID 24304549, 2013). "Genes of known importance in breast cancer and estrogen signaling, including ERBB2, PGR, MYC, CLU, and NCOA2, were among those identified as Sin3A-responsive." (PMID 20920219, 2010). "In in vitro experiments in breast cancer cell lines with different nuclear receptor status (MDA-MB-231, ERα-, PR–, and HER2–; T47D, ERα+, PR+, and HER2-; MCF7, ERα+, PR+, and HER2+/–), we demonstrated that NCOA2 knockdown strongly inhibited cancer cell growth." (PMID 30941313, 2019). "We detected selective recruitment of NCOA3 but not NCOA1 or NCOA2 to the PLAC1 promoter only in ERα-positive MCF-7 cells but not in ERα-negative SK-BR-3 breast cancer cells." (PMID 24304549, 2013). "In sum, the loss of HDAC1 and HDAC2 increases C3 and NCOA2, but not CLU, ERBB2, MYC, or PGR, providing evidence that C3 and NCOA2 are repressed in breast cancer cells by the HDAC1/2 components of the Sin3A repressive complex." (PMID 20920219, 2010). "In a first experiment, we analyzed expression of NCOA1, NCOA2 and NCOA3 in ERα-positive MCF-7 and ERα-negative SK-BR-3 breast cancer cells that both have been shown to express PLAC1 protein." (PMID 24304549, 2013).
sarcoma (10 papers, 2014 to 2026). A usually aggressive malignant neoplasm of the soft tissue or bone. "No specific line of differentiation was found by immunohistochemical staining, and an RNA-based fusion panel revealed a MEIS1::NCOA2 fusion, at which point a diagnosis of Low-Grade Undifferentiated Sarcoma with MEIS1::NCOA2-Rearrangement was rendered." (PMID 38678288, 2024). "For instance, similar mechanisms may occur in other FET-fused sarcomas or MAML3- or NCOA2-fused sarcoma, which also contain PrLD domains." (PMID 38611033, 2024). "MEIS1::NCOA2/1 fusion sarcoma is a rare, recently recognized spindle cell neoplasm defined by a characteristic gene fusion involving MEIS1 and NCOA2 or, less commonly, NCOA1." (PMID 41463261, 2025).